CRP (C-reactive protein)
Diseases named in the same sentence as CRP in open-access papers (continued):
Sharing a sentence is not in itself a finding about the gene and the disease.
tumor (continued). "In the combined analysis of all 364 patients, CRP ≥0.2 mg/dL (HR 3.87; 95%CI 1.65–9.07; p = 0.002), metastases (HR 2.80; 1.49–5.25; p = 0.001), tumor size ≥3 cm (HR 1.83; 95%CI 1.05–3.16; p = 0.034), and age (HR 1.56 per 10 years; 95%CI 1.24–1.97; p < 0.001) remained significant factors for OS." (PMID 32423000, 2020). "Investigators have reported that plasma CRP concentrations are increased in response to inflammation, which may promote tumor growth and metastasis in breast cancer and ovarian cancer." (PMID 33208875, 2020). "In summary, our large dataset of elderly HNSCC patients shows the prognostic strength of the blood parameters hemoglobin, GFR, CRP and albumin, representing established features of the tumor and normal tissue biology such as oxygenation, kidney function, inflammation and nutritional status." (PMID 32604773, 2020). "Our data showed that CRP is an enhancer of MDSC generation and suppressive function and CRP can also inhibit dendritic cell function; therefore we predict that compared to wild type mice, CRPtg should have more MDSCs and more tumor burden while the inverse should be seen in CRP−/− mice." (PMID 33633738, 2020). "Considering that CRP also affects tumor progression, more effort in explicating its role in the tumor might be beneficial in understanding the connection between tumor and human innate immunity." (PMID 33013829, 2020). "The proportion of high-level CRP share was 72% in the group with tumor size > 10 cm, proportion of high-level CRP share in the group with tumor size 5–10 cm was 61%, and the proportion of patients with high-level CRP was 87% in the group with tumor size ≤ 5 cm." (PMID 33208875, 2020). "Plasma CRP has been proposed as a sensitive serological surrogate parameter for elevated levels of pro-inflammatory cytokines stimulating angiogenesis, tumor proliferation, and growth and represents an easily measurable, blood-based biomarker routinely analyzed before the initiation of treatment." (PMID 33023215, 2020). "For continuous variables, optimal cut-off values were selected by the ROC curve analysis, which were 60 years for age, 5.0 cm for tumor size, 5.00 mg/dL for serum C-reactive protein (CRP) level, 2.30 for NLR, 173.76 for PLR, 4.65 for SUVmaxT, − 90.60 for VAT attenuation, and 0.46 for VAT SUV." (PMID 31485803, 2020). "Thus, we aimed to analyse the prognostic role of tumour PD-L1 expression and routinely available pathological and clinical biomarkers including Ki-67 index and circulating C-reactive protein (CRP) levels in patients diagnosed with MPE." (PMID 32238865, 2020). "Abnormal levels of CRP and Alb have been related to poor prognosis of tumor patients." (PMID 33008382, 2020). "Second, CRP is an indicator of an immune response to tumor antigens." (PMID 33351844, 2020). "IL-6 plays an important role in the tumor-related systemic inflammatory response, not only as a major inducer of CRP but also as a direct inducer of anti-inflammatory molecules, which are also considered potential mechanisms by which IL-6 participates in the occurrence of irAEs." (PMID 33317597, 2020). "GNRI values were significantly associated with age (p < 0.001), BMI (p < 0.001), RBC (p < 0.001), albumin (p < 0.001), CRP (p < 0.001), tumor size (p < 0.001), operative procedure (p = 0.043), depth of tumor (p < 0.001), pathological stage (p < 0.001), and intraoperative blood loss (p = 0.029)." (PMID 32595832, 2020). "The patient presented with increased LDH and C-reactive protein (CRP); elevated tumor markers (CA-125, NSE); positivity for plasma EBV-DNA and CMV-DNA; negativity for HIV, hepatitis C and hepatitis B antigen test; and a negative tuberculosis-interferon gamma release assay (TB-IGRA) test." (PMID 32664092, 2020). "Only then, the information on CRP serum concentrations in type 1 EC could be evaluated in relation to tumor stage or prognosis and could be used to support decisions about adjuvant chemotherapy." (PMID 32977765, 2020).
tumor (continued). "Furthermore, the correlation of acupuncture and moxibustion with T-bet/IFN-γ, GATA3/IL4, inflammation markers IL-6 and C-reactive protein (CRP), and tumor marker Ca199 was evaluated." (PMID 33144870, 2020). "Through these methods it may be possible to fully dissect the impact of CRP on the interactions between tumor and stromal compartments in order to assess its role in tumor development and metastasis." (PMID 33324413, 2020). "Patients with higher tumor stages typically presented with higher preoperative CRP levels." (PMID 33080990, 2020). "CRP, as a representative acute phase reactant, is part of the nonspecific immune mechanism that reflects the presence of systemic inflammation in the host and represents a high level of immunogenicity and tumor burden." (PMID 33317597, 2020). "The increased CRP level is often found in patients with neoplastic diseases, including PA." (PMID 33316933, 2020). "There is evidence that CRP itself exerts pro-inflammatory and tumor-promoting effects." (PMID 33023215, 2020). "However, few studies have explored the role of CRP as a predictor of tumor recurrence and prognosis before the treatment of patients with HNSCC." (PMID 33201589, 2020). "Anti-GD1b, GT1b, and GQ1b antibodies that are negatively correlated with IL-8 and CRP suggest that they could indirectly suppress tumor growth and angiogenesis." (PMID 32855975, 2020). "Univariate analysis revealed that IRE treatment, tumor grade, ALB, and CRP were associated with OS." (PMID 32410380, 2020). "The decline of CRP in patients who respond to antineoplastic treatment may be related to a decreased secretion of tumor derived proinflammatory cytokines coming along with tumor shrinkage." (PMID 32824580, 2020). "Thus, the occurrence of PMV was associated with an impaired preoperative functional constitution, an increased CRP value and a larger tumor size." (PMID 33396290, 2020). "First, pre-operative CRP is not so much caused by pre-existing inflammatory disease but by tumor-associated factors, such as tumor type and burden." (PMID 33080990, 2020). "In this potential scenario, high CRP levels may be considered as the systemic response to a pro-inflammatory, pro-tumoral condition developing at tumor site." (PMID 32646072, 2020). "If we consider the relationship between serum concentrations of the tested proteins and the histological type of OC, CXCL-8 levels, similarly to those of the classical tumor markers and CRP, were significantly higher in patients with OSCC in comparison with subjects with OAC." (PMID 30820705, 2019). "Furthermore, CRP is an acute reactant protein that is increasingly expression in the presence of infection, trauma, tissue necrosis, tumor, and several types of inflammatory diseases." (PMID 31148582, 2019). "As Hsp70 serum concentrations increased concomitantly with C‐reactive protein (CRP) between V2 and V4 (exHsp70: 22 ± 2.6 ng/ml), it was assumed that inflammation rather than tumor growth caused this increase." (PMID 30747241, 2019). "In the total OC group, the AUC of CXCL-8 (0.8315; p < 0.001) was lower than the AUC of CRP (0.9092; p < 0.001), but higher in comparison with the AUCs of the classical tumor markers (CEA = 0.5238; p = 0.719 and SCC-Ag = 0.8250; p < 0.001) in the diagnosis of OC." (PMID 30820705, 2019). "In order to serially map the homeostatic anti-tumor immune response-fluctuations, High Sensitive C-Reactive Protein (HS-CRP), Lactate Dehydrogenase (LDH) and Lymphocyte/Monocyte Ratio (LMR) were analyzed using high-order polynomial trend analysis as surrogate of immune system response." (PMID 31801549, 2019). "Elevated serum CRP is associated with HCC recurrence after LT and may be a marker for more aggressive tumor biology." (PMID 31141535, 2019). "Unlike previous studies, our study indicated that neither CRP nor NLR was associated with tumor regression." (PMID 30867256, 2019). "CRP is released by the liver upon IL-6 signaling that in turn promotes tumor progression." (PMID 31788452, 2019).
tumor (continued). "The optimal cut-off values for continuous variables were 60 years for age, 3.0 cm for tumor size, 5.0 mg/dL for serum CRP level, 2.75 for NLR, 201.00 for PLR, 6.60 for maximum SUV, 8.50 cm3 for metabolic tumor volume, 32.50 g for total lesion glycolysis, 1.82 for BM SUV, and 0.85 for BLR." (PMID 31382679, 2019). "In conclusion, serum CRP may represent a valuable surrogate parameter for a more aggressive tumor biology." (PMID 31141535, 2019). "In several studies, experts have already suggested that a lower threshold for CRP (cutoff value: 0.3 mg/dL) may enhance the prognostic value of the GPS in tumor patients." (PMID 31819103, 2019). "Spearman’s correlation indicated that there was a significant correlation between serum CXCL-8 concentrations, depth of tumor invasion (T factor) (p = 0.010) and CRP concentrations (p = 0.003), while a positive correlation existed between SCC-Ag concentrations and TNM stage (p = 0.030)." (PMID 30820705, 2019). "Moreover, statistically significant differences were found also between the depth of tumor invasion (T factor) and CRP (p = 0.021) as well as between T factor and SCC-Ag levels (p = 0.009)." (PMID 30820705, 2019). "In addition, suppressive immune features indicating a poor prognosis of SCLC include the frequency of CD14+HLA-DR-/low myeloid-derived suppressor cells (MDSCs), the C-reactive protein/albumin (CRP/Alb) ratio and a higher Treg cell ratio in tumor infiltrates." (PMID 31253167, 2019). "In addition, the change in weight, pain and quality of life, as well as the type of tumor removal surgery, hormone therapy and the uMARS score, can have a contribution in the changes found in the concentrations of CRP and IL-6." (PMID 31414667, 2019). "This tumor-related inflammatory response can be reflected by hematological parameters like, amongst others, a high leukocyte count, elevated C-reactive protein (CRP), or the ratios of different cell types, e.g., the neutrophil-to-lymphocyte ratio (NLR)." (PMID 31108935, 2019). "Furthermore, we combined the NLR and the CRP into a single variable and found a significant difference in tumor regression between the NLR-CRP-high group and the NLR-CRP-low group (P=0.022)." (PMID 30867256, 2019). "Some studies have indicated that CRP level is positively correlated with tumour progression." (PMID 30976022, 2019). "CRP levels in both serum and tumor tissue could be evaluated among various solid tumors for prognostic purposes." (PMID 30138391, 2018). "Tumor tissue can trigger inflammatory response, further promotes the accumulation of inflammatory cells and the release of pro-inflammatory cytokines, resulting in an increased production of CRP by hepatocytes." (PMID 29568406, 2018). "The following variables significantly differed between the SSI and non-SSI groups: surgical time, diameter of the skin incision, maximum tumor diameter, instrumentation, presence of an open wound, preoperative chemotherapy, preoperative CRP concentration, and preoperative GNRI." (PMID 30513989, 2018). "RCC is a tumor, producing directly CRP, not only mediated via liver." (PMID 30424016, 2018). "Interestingly, there was evidence in indoximod-treated patients of increased levels of both C reactive protein (CRP) and autoantibodies to tumor antigens, consistent with an increased inflammatory response to the chemotherapy onboard." (PMID 30254983, 2018). "High CRP has also been reported to predict poor prognosis in many tumor types." (PMID 29624591, 2018). "There were significant intergroup differences in age (year), number of tumors, maximum tumor diameter (mm), CRP (mg/dL), albumin (g/dL), globulin (g/dL), WBC count (×103/mm3), platelet count (×104/mm3), CEA (ng/mL), CA19‐9 (U/mL), and NLR (Mann–Whitney U‐test)." (PMID 30460347, 2018). "Additionally, tumor cells have been proposed as a potential trigger for CRP upregulation, as they secrete IL-6 and 8 to stimulate liver CRP production." (PMID 29619344, 2018).
tumor (continued). "Based on this, we hypothesized that the detection of elevated CRP levels during oncologic surveillance might be helpful to predict tumor recurrence, and suggested CRP serum concentration monitoring might be included in the surveillance of patients with TETs." (PMID 29774108, 2018). "An elevated NLR was significantly associated with the tumour size (P < 0.001), Fuhrman-grade (P = 0.011), TNM stage (P < 0.001), pT status (P = 0.001), pN status (P < 0.001), tumour thrombus (P = 0.014), CRP/Alb (P < 0.001), PLR (P = 0.001), LDH (P = 0.014) and proteinuria (P < 0.013)." (PMID 29890986, 2018). "A third proposed mechanism states that the body’s innate and adaptive immune systems may react to tumor antigens by increasing CRP levels." (PMID 29668751, 2018). "Both, serum IL-8 and CRP, correlated with tumor size and with macrophage infiltration." (PMID 29515790, 2018). "CRP levels showed a graded increase according to the severity of the tumour." (PMID 30539028, 2018). "Other significant independent prognostic factors for survival were ECOG-PS, tumor type, and CRP." (PMID 29879960, 2018). "CRP levels in OSCC patients were elevated and were associated with advanced tumor stages." (PMID 30842796, 2018). "Elevated CRP levels may contribute to create a favorable microenvironment for tumor cells proliferation and metastatization." (PMID 29568406, 2018). "Recent clinical surveys found that serum concentrations of prealbumin negatively correlate with levels of vascular endothelial growth factor and C-reactive protein, suggesting the connection between nutritional impairment and tumor metastasis and systemic inflammation in patients with OC." (PMID 29254237, 2017). "Therefore, the information of CRP serum concentrations in oncologic patients can only be interpreted in relation to tumor stage or prognosis after all the information of possible other reasons for CRP elevation has been valued." (PMID 28514756, 2017). "In this study, CRP elevation and tumor status presented a clear positive correlation." (PMID 28209200, 2017). "Altogether the origin and pathogenesis of “tumor CRP” in patients with TETs remain elusive." (PMID 28514756, 2017). "However, we found accurate PPV of 71.4% and NPV of 88.9%, indicating that CRP could be a cheap, commonly available and established routine serum marker that might be helpful, especially in oncologic follow-up to identify patients with increased risk of tumor recurrence." (PMID 28514756, 2017). "However, they failed to independently predict prognosis in the multivariate analysis, indicating that they reflect tumor burden less sensitively and less precisely than the CRP/Alb ratio." (PMID 28676731, 2017). "Furthermore, CRP levels were recently suggested as a prognostic factor in patients undergoing tumor resection for intrahepatic CCA25." (PMID 29208940, 2017). "Significant correlations could be found between overall survival and dichotomously separated patient or disease characteristics, namely for ECOG status, CLIP score, preceding tumor surgery, CRP, AFP and LDH concentrations in serum at study inclusion." (PMID 29098441, 2017). "We noted that CRP/Alb correlated significantly with advanced tumor stage, residual tumor, increased CA-125 levels and the presence of ascites, suggesting that increased CRP/Alb may correlate with a more aggressive disease phenotype." (PMID 28431566, 2017). "Furthermore, we analyzed the prognostic value of CRP/Alb combined with tumor stage and residual tumor." (PMID 28431566, 2017). "Additionally, immunohistochemical tumor CRP expression and serum concentrations of interleukin (IL)-6 and IL-1β were measured." (PMID 28514756, 2017). "Since it could be easily calculated from the routine clinical laboratory tests, testing the CRP/Alb ratio could be used as a simple, feasible, inexpensive method to predict prognosis and to monitor the dynamic change of tumor burden." (PMID 28676731, 2017).
tumor (continued). "Moreover we attempted to elucidate the pathogenesis and origin of “tumor-CRP” in patients with TETs." (PMID 28514756, 2017). "Such inflammatory setting could favor tumor progression while modifying levels of routine blood parameters such as C-reactive protein (CRP), leukocytes and derivatives." (PMID 27209168, 2017). "The role of tumor-derived CRP in tumor immunity is less clear, but it may impair dendritic cell function by reducing their migration activity." (PMID 28978752, 2017). "Patients in the training cohort with left-sided colon cancer had early tumor stages, higher inflammatory index (CRP, pateletes, PLR, NLR, CAR, mGPS), higher tumor marker CEA, higher ALB and higher probability of microsatelite stability in the univariate analysis." (PMID 29262803, 2017). "Furthermore, the preoperative serum CRP level appeared independent from tumor characteristics and treatment allocation." (PMID 27733196, 2016). "After adjusting for the UICC stage and other important factors including gender, age, smoking status, first-degree family history of NPC, BMI, and CRP level, a Cox regression analysis confirmed the prognostic value of the tumor CTLA-4 expression, particularly the D-FFS, in NPC patients." (PMID 26918337, 2016). "Moreover, immune modulators, including TGF β, IL10 and CRP, released by tumor cells impair lymphocyte action in systemic inflammation." (PMID 27198767, 2016). "In our present paper, the serum concentrations of CXCL12 were significantly higher, while CXCR4 was significantly lower in EC patients compared to healthy controls, while the levels of classical tumor markers as well as CRP were found to be also higher in EC patients than in control group." (PMID 27041792, 2016). "Finally, serum CRP has also been evaluated in conjunction with TK1 with a calculated Neoplasia Index (NI) value resulting." (PMID 27747218, 2016). "A new scoring model was developed, consisting of BMI, CRP, and tumor T and N classification." (PMID 26980738, 2016). "Elevated CRP could be a marker for chronic inflammation in the tumor microenvironment, with chronic inflammation itself also acts as a stimulus for angiogenesis, cell proliferation, and tumorigenesis." (PMID 26292957, 2015). "Treatment response or tumor stage: CRP predicted treatment response in six studies." (PMID 26717416, 2015). "In order to explore whether CRP predicts the outcome of specific patients, we extracted the data on treatment and tumor stage." (PMID 26235332, 2015). "Tumoral CRP (increased locally within the tumor) may be superior to serum CRP for prognosis and recurrence." (PMID 26717416, 2015). "Second, CRP could represent an indicator of an immune response of the host to tumor antigens or necrosis." (PMID 26248232, 2015). "These properties may increase the importance of SAA or CRP-SAA in tumor pathogenesis and metastasis." (PMID 26264146, 2015). "High CRP predicted prognosis in most reports (90%) in these two tumor groups." (PMID 26717416, 2015). "In three studies, elevated CRP independently predicted both tumor recurrence and prognosis." (PMID 26717416, 2015). "We also examined the role of CRP to predict treatment response and tumor recurrence." (PMID 26717416, 2015). "A temporary inflammatory reaction was observed on post-admission day 8, indicated by a CRP level of 8.1 mg/dl, and it was hypothesized that necrosis of the tumor progressed over the same period." (PMID 25788993, 2015). "One is that tumor growth promotes tissue inflammation and increases the level of CRP." (PMID 25999661, 2015). "By contrast, three variables of ECOG score, CA19-9 levels, and CRP levels identified in our prognostic index model represent the general condition, tumor burden, and systemic inflammatory reaction of patient, respectively, making our result more close to clinical practice." (PMID 25792009, 2015).